AKAP12 (A-kinase anchoring protein 12)
Description:
Anchoring protein that mediates the subcellular compartmentation of protein kinase A (PKA) and protein kinase C (PKC).
Synonyms: AKAP250; SSeCKS
Tractability: Antibody: its Gene Ontology location is reachable by antibodies, with high confidence; the Human Protein Atlas places it where antibodies can reach. PROTAC: UniProt records ubiquitination sites on it; ubiquitination databases record sites on it; its protein half-life has been measured.
Gene: Protein-coding gene on chromosome 6 (151,239,936 to 151,358,563, forward strand). Ensembl gene ENSG00000131016.
Subcellular location: Cytoplasm, cell cortex; Cytoplasm, cytoskeleton; Membrane
Subcellular location (Human Protein Atlas): Cytosol; Plasma membrane
Pathways (Reactome):
Signal Transduction: RHOD GTPase cycle; RHOF GTPase cycle
Gene Ontology:
Molecular function: adenylate cyclase binding; protein binding; protein kinase A binding; calmodulin binding
Biological process: adenylate cyclase-inhibiting G protein-coupled receptor signaling pathway; G protein-coupled receptor signaling pathway; signal transduction; cAMP/PKA signal transduction; cellular response to interleukin-1; cellular response to tumor necrosis factor; hepatic stellate cell activation; negative regulation of vascular permeability; positive regulation of ERK1 and ERK2 cascade; positive regulation of hepatic stellate cell migration; positive regulation of oligodendrocyte apoptotic process; positive regulation of tumor necrosis factor production; regulation of protein kinase C signaling; response to electrical stimulus; response to lipopolysaccharide
Cellular component: cytosol; focal adhesion; plasma membrane; cytoplasm; cell cortex; cytoskeleton; membrane; neuronal cell body
Genetic constraint (gnomAD): Loss-of-function variants: 28 observed, 77.46 expected, observed/expected ratio (o/e) 0.36, 90% interval 0.27 to 0.5. The upper end of that interval is the gene's LOEUF score, 0.5, which puts it in group 2 of 6, group 1 being the genes least tolerant of losing a copy. Missense variants: 2,038 observed, 2,217 expected, observed/expected ratio (o/e) 0.92, 90% interval 0.88 to 0.95. Synonymous variants: 790 observed, 861.95 expected, observed/expected ratio (o/e) 0.92, 90% interval 0.86 to 0.97.
Homologues: Orthologues: chimpanzee AKAP12 (99% identical), macaque AKAP12 (94% identical), pig AKAP12 (66% identical), rabbit AKAP12 (65% identical), dog AKAP12 (65% identical), guinea pig AKAP12 (57% identical), mouse Akap12 (56% identical), rat Akap12 (54% identical), tropical clawed frog akap12 (33% identical), zebrafish akap12b (24% identical), zebrafish akap12a (17% identical).
Diseases named in the same sentence as AKAP12 in open-access papers:
AKAP12 is named in the same sentence as 114 diseases in open-access papers, as found by Europe PMC text mining. Sharing a sentence is not in itself a finding about the gene and the disease. The quoted sentences say what the papers report.
prostate carcinoma (23 papers, 2011 to 2024). A carcinoma that arises from epithelial cells of the prostate gland. "AKAP12 is known as a tumor suppressor protein reduced in the metastatic progression of human prostate cancer, and loss of the AKAP12 gene induced prostatic hyperplasia in mice." (PMID 24760034, 2014). "In addition, compared to primary-site lesions, roughly a third of prostate cancer metastases show chromosomal loss of the AKAP12 locus in 6q24-25.2." (PMID 29050279, 2017). "CircEXOC6B can bind with RBMS1 and HuR and elevate AKAP12 (A-kinase anchoring protein 12) expression levels, leading to inhibition of tumor metastasis in prostate cancer." (PMID 38152652, 2023). "The lncRNA MALAT1 acts through the miR-145-5p/A-kinase anchoring protein 12 (AKAP12) axis to influence prostate cancer therapy." (PMID 34079751, 2021). "For example, the lncRNA MALAT1 is overexpressed with high risk HPVs infection while the lncRNA MALAT1/miR-145-5p/AKAP12 axis has been verified in prostate cancer." (PMID 32849815, 2020). "MALAT1 has also been shown to confer resistance to Docetaxel (DTX) resistance via A-kinase anchoring protein 12 (AKAP12) in prostate cancer (Pca) cells." (PMID 31777593, 2019). "Lastly, future studies will elucidate how the miR-186-5p-AKAP12 axis and other miR-186-5p targets play a role in prostate cancer using in vitro and in vivo models." (PMID 29653561, 2018). "Although hundreds of potential miR-186-5p targets were identified in the miR-186-5p depleted PC-3 cells, we focused on AKAP12, a validated target involved in prostate cancer." (PMID 29653561, 2018). "The siRNA-mediated knockdown of human SSeCKS/AKAP12 in DU145 prostate cancer cells resulted in increased chemotaxis to serum, whereas its overexpression in MDA-MB-231 breast cancer cells inhibited chemotaxis." (PMID 25356636, 2014). "Furthermore, miR-95-3p is upregulated in prostate cancer tissues and correlates with poor prognosis, while it also affects the progression of triple-negative breast cancer by targeting AKAP12 expression." (PMID 38827810, 2024). "Interestingly, the loss of AKAP12 and ZNF483 expression were described in prostate cancer and acute lymphoblastic leukemia, respectively; on the other hand, AFTPH was the most up regulated circRNA in our analysis." (PMID 37106694, 2023). "Downregulation of AKAP12 may act as a candidate tumor biomarker of several malignancies, such as prostate cancer, breast cancer, gastric cancer and hepatocellular carcinoma." (PMID 31384238, 2019). "In a more recent study, it was shown that the combined loss of RB and Akap12, a gene shown to function as a metastasis suppressor in prostate cancer, results in prostatic intraepithelial neoplasia that fails to progress to prostate cancer." (PMID 31366128, 2019). "For example, the time-to-onset of castration-recurrent prostate cancer correlating with AKAP12 loss is roughly three times less than cases without AKAP12 loss." (PMID 30323895, 2018). "Although data for melanoma-associated stroma are not available, stroma isolated from prostate cancers exhibit decreased AKAP12 expression compared to that in normal or hyperplastic stroma, and this does not correlate with increased tumor inflammation." (PMID 30323895, 2018). "Loss of AKAP12 expression is noted in the tumor stroma in breast and prostate cancer, compared to non-tumor-associated stroma." (PMID 30323895, 2018). "AKAP12 (also known as SSeCKS, Gravin or AKAP250) functions as a metastasis suppressor in prostate cancer models based on its ability to scaffold kinases such as Src, PKC and PKA, and to suppress their activation of downstream signaling mediators." (PMID 37292818, 2023). "Several direct targets have been identified, including AKAP12 in hepatocellular carcinoma, PTEN in non-small-cell lung cancer and D52 in prostate cancer, have been reported to be targets of miR-103a-3p." (PMID 35094292, 2022).
prostate carcinoma (continued). "In the five types of controversial cancers (NSCLC, bladder cancer, prostate cancer, colorectal cancer, pancreatic cancer), several reports showed miR-186 served as an oncomir by suppressing targets PTEN, PPM1B, RETREG1, AKAP12, or NR5A2." (PMID 32195180, 2020). "Using the Cancer Genome Atlas (TCGA) dataset, we observed that high expression of CTBP2 was significantly correlated with poor overall survival of prostate cancer patients, while AKAP12, HIF1A and RHOB were not." (PMID 38698344, 2024).
breast carcinoma (17 papers, 2012 to 2025). "AIF1 has been demonstrated to reinforce the resistance of breast cancer cells to cisplatin by inhibition of cell apoptosis and reduction of intracellular cisplatin accumulation and AKAP12 is associated with paclitaxel-resistance in serous ovarian cancer." (PMID 36417130, 2023). "Loss of AKAP12 has been shown to increase cancer incidence and metastatic spread in several cancers including prostate and breast cancer." (PMID 29433456, 2018). "The gene encoding the human SSeCKS orthologue, Gravin, is localized on chromosome 6q24-25.2, a deletion hotspot in advanced prostate, ovarian, and breast cancer, implicating a role for the loss of AKAP12 in cancer progression." (PMID 22811901, 2012). "We noted that AKAP12 total protein level was significantly decreased in breast cancer, colon cancer, HNSC, hepatocellular carcinoma (HCC), LUAD, OV, and UCEC tissues in comparison with normal tissues (p < 0.05)." (PMID 36110213, 2022). "A recent study has demonstrated that AKAP12 expression was reduced in breast cancer and repressed chemotaxis-induced cell migration through regulating F-actin." (PMID 36110213, 2022). "For instance, the expression level of AKAP12 is downregulated in breast cancer, leukemia, ovarian cancer, colorectal cancer, and hepatocellular carcinoma." (PMID 22811901, 2012). "Among these concordantly methylated genes, several have known tumor-suppressive activities in PCa, including ERBB4, MCPH1, RBMS3, and AKAP12, High DNA methylation levels of ERBB4 have been associated with poor prognosis and aggressive disease in breast cancer patients." (PMID 40723280, 2025). "Among the predictions with the lowest scores, MTDH has been shown to epigenetically regulate TWIST1 and promote stemness in breast cancer while AKAP12 has been suggested to protect ERK5 from PKCζ phosphorylation on residue S486A which inhibits its transcriptional activity." (PMID 37420093, 2023). "AKAP12, another member of this same complex, plays a significant role in phosphorylation-dependent cell cycle progression and nucleocytoplasmic shuttling to facilitate DNA repair, implying alteration of these activities in ER + breast cancer." (PMID 35831314, 2022). "Interestingly, AKAP5, AKAP9, AKAP11 and AKAP12 is expressed at lower levels in the basal-like and, less prominently in HER2-enriched subtypes, the breast cancer subtypes with highest risk of recurrence." (PMID 29433456, 2018). "Preliminary analysis of Oncomine data indicates that SSeCKS/AKAP12 levels are also downregulated in the tumor-associated stroma of prostate and breast cancer relative to stroma in non-neoplastic control tissue." (PMID 29050279, 2017). "As a result, the patients harboring ESR1->AKAP12 fusion may exhibit different responses to breast cancer hormone therapy." (PMID 24727804, 2014). "Through analysis of RNA-sequencing data in breast cancer, recurrent intragenic fusions of 5′ end of ESR1 and the 3′ ends of AKAP12, ARMT1 or CCDC170 amongst other genes have been identified." (PMID 35151276, 2022). "The expression of AKAP12 has been verified to be decreased in multiple cancers, including hepatocellular carcinoma (HCC), CRC, and breast cancer." (PMID 36110213, 2022). "In breast cancer (BC), recurrent fusion genes of estrogen receptor alpha (ESR1) and AKAP12, ARMT1 and CCDC170 have been reported." (PMID 35151276, 2022). "The presence of the ESR1 fusions with AKAP12, ARMT1 and CCDC170 (exon 2 to exon 11) was evaluated in breast cancer tissue samples from 732 breast cancer patients." (PMID 35151276, 2022).
colon cancer (12 papers, 2011 to 2024). "A recent report using microarray data from in silico genetic searches indicated that methylation is associated with the downregulation of AKAP12 in colon cancer and identified AKAP12 as a potential tumor suppressor gene candidate." (PMID 21918680, 2011). "AKAP12 is involved in promoting colon cancer metastasis via HDAC6-dependent AKAP12 deacetylation and ubiquitination mediated degradation." (PMID 38365849, 2024). "For example, the deacetylation of AKAP12 at K531 by HDAC6 can increase its level of ubiquitination, promotes the proteasome‐dependent degradation of AKAP12 and facilitates colon cancer metastasis." (PMID 38783893, 2024). "Not only in SOC, the elevated proteins of PER1, AKAP12 and MMP17 are also associated with the migration and invasion in triple-negative breast cancer, melanoma and colon cancer." (PMID 37434173, 2023). "Exogenous overexpression of AKAP12 in Lovo colon cancer cell line inhibits tumor cell proliferation, migration, and invasion ability; in contrast, AKAP12 silencing or AKAP12/HDAC3 cosilencing promotes tumor cell proliferation, colony-forming ability, and cell cycle progression." (PMID 36148016, 2022). "AKAP12 has also been described as being induced in colon cancer cells." (PMID 34503224, 2021). "Deacetylation of AKAP12 at K531 by HDAC6 increases its ubiquitination, which facilitates AKAP12 proteasome-dependent degradation to promote colon cancer metastasis." (PMID 39247591, 2024). "Using two GEO datasets (GSE64472 and GSE86525), significantly increased the expression of AKAP12 was validated in vandetanib-resistant NSCLC and BV-resistant colon cancer." (PMID 36110213, 2022). "Moreover, the elevated expression of AKAP12 was also validated in vandetanib-resistant NSCLC and BV-resistant colon cancer." (PMID 36110213, 2022).
hepatocellular carcinoma (11 papers, 2015 to 2022). A malignant tumor that arises from hepatocytes. "AKAP12 has been associated with certain human cancers, including lung carcinoma and hepatocellular carcinoma." (PMID 26967563, 2016). "AKAP12 overexpression decreased hepatocellular carcinoma (HCC) cell proliferation, migration and invasion through targeting by miR-1251-5p." (PMID 36253873, 2022). "Additionally, miR-183 may act to reduce the expression of the tumor suppressor gene AKAP12 in hepatocellular carcinomas." (PMID 33653339, 2021).
meningioma (10 papers, 2018 to 2024). A generally slow growing tumor attached to the dura mater. "Collectively, these data support a role for AKAP12 in suppressing invasive and proliferative phenotypes associated with meningioma malignancy." (PMID 29391485, 2018). "By using two high-throughput technologies: unbiased iTRAQ LCMS/MS and biased Pamchip peptide arrays, it was found that the A-kinase anchor protein 12 (AKAP12) protein (a phosphoprotein) is downregulated in all grades of meningioma." (PMID 32983987, 2020). "AKAP12 has been reported as a central regulator of meningioma aggressiveness with a possible role in progression." (PMID 32974197, 2020). "Further studies have shown that knocking down AKAP12 in benign meningioma cells promotes proliferation, migration, and invasion, suggesting that AKAP12 is a central regulator of invasive meningioma progression." (PMID 32983987, 2020). "It has been found that knock-down of AKAP12 can promote the migration and invasion of meningioma cells, indicating that AKAP12 plays a possible role in inhibition of the progression of meningioma." (PMID 33042832, 2020). "We silenced AKAP12 expression in benign meningioma cells, leading to dysregulation of cell cycle, proliferation, migration and invasion." (PMID 29391485, 2018). "We have observed higher AKAP12 levels in irradiated meningioma cell lines (unpublished observations)." (PMID 29391485, 2018). "Integration of the phosphoproteome and kinome datasets confirmed the function of AKAP12 in high-grade meningioma signaling." (PMID 29391485, 2018). "Our results demonstrate that AKAP12 functions as a tumor suppressor in meningioma and regulates cell cycle, influencing cell proliferation, migration and invasion." (PMID 29391485, 2018). "Our results demonstrate hyperphosphorylation of RB1 Ser780 and increased CCND1, CDK4, and CDK6 expression in high-grade meningiomas and after AKAP12 knockdown." (PMID 29391485, 2018). "AKAP12 in its phosphorylated and unphosphorylated state was decreased in high-grade meningioma tissue and cell lines." (PMID 29391485, 2018). "Inactivation of the PKA pathway in aggressive meningiomas is also seen despite possible cAMP activation and that AKAP12 silencing downregulates PKA signaling in meningioma." (PMID 29391485, 2018). "Nearly 62.0% (21/34) and 68.5% (41/60) of AKAP12 downstream targets were found dysregulated in meningioma grade II and III, respectively." (PMID 29391485, 2018). "AKAP12 originally showed decreased levels of phosphorylation on Ser1587 across the meningioma grades in the iTRAQ LC MS/MS dataset." (PMID 29391485, 2018). "AKAP12 is expressed in low levels in these higher-grade tumors and when it is silenced in meningioma cells, a decrease in PKA signaling results." (PMID 29391485, 2018). "Simultaneous kinome profiling after AKAP12 silencing and high-grade meningiomas showed a 60% overlap, demonstrating potential for identification of prognostic biomarkers and therapeutic targets." (PMID 29391485, 2018). "Here we report the kinomic and phosphoproteomic signatures of high-grade meningiomas, the biomarker potential and regulatory role of AKAP12 in meningioma malignancy." (PMID 29391485, 2018). "The AKAP12 expression in different meningioma grades revealed lower AKAP12 expression in high-grade specimens (one-sided Spearman correlation p = 0.032, one-sided rank-regression p = 0.034)." (PMID 29391485, 2018). "Since kinase inhibitors have played an important role in cancer treatment, we also explored kinase activity regulated by the AKAP12 in high-grade meningiomas." (PMID 29391485, 2018).